INS (insulin)
Diseases named in the same sentence as INS in open-access papers (continued):
Sharing a sentence is not in itself a finding about the gene and the disease.
type 2 diabetes (continued). "The complex interplay between insulin secretion, insulin sensitivity, and dietary habits in relation to glucose metabolism led us to hypothesize that type 2 diabetes risk loci including CDKAL1 could exert some protective effects on fat accumulation, which was represented by BMI in the present study." (PMID 23173044, 2012). "As insulin and its receptors are both known to be expressed and to govern important functions in the brain, it seemed reasonable to search for altered gene expression patterns in animal models of type 1 and type 2 diabetes characterized by absolute or relative insulin deficiency." (PMID 22369239, 2012). "Inflammation induced by the release of beta cell cytokines also plays a role in type 2 diabetes, but in this case it arises from endoplasmic reticulum stress caused by excessive nutrient uptake (collectively called glucotoxicity and lipotoxicity) and insulin production." (PMID 22460761, 2012). "While the biological roles of miRNAs in adipose tissue remain mostly unknown, reduced circulating levels of one of the MLX-regulating miRNAs—mmu-mir-29b—has been associated with the development of type 2 diabetes, and the mmu-mir-29 family may be involved in insulin signaling." (PMID 22629440, 2012). "A recent review indicates that vitamin D deficiency may predispose to glucose intolerance, altered insulin secretion and type 2 diabetes, either through a direct action via vitamin D receptor (VDR) activation or indirectly via calcemic hormones and also via inflammation." (PMID 22347618, 2012). "In addition, high insulin index is implicated in promoting complications of type 2 diabetes." (PMID 23304216, 2012). "Nearly four decades ago, the bihormonal-abnormality hypothesis established the essential role for glucagon in diabetes, by highlighting the contributions of deficient insulin secretion, development of insulin resistance and increased glucagon secretion to the hyperglycemic state in type 2 diabetes." (PMID 22479612, 2012). "Moreover, SP-D is found positively associated with insulin sensitivity, suggesting that decreased SP-D expression could be behind the association of lung function with impaired insulin actions in type II diabetes." (PMID 22509382, 2012). "More recently, retinol binding protein-4 (RBP4), an adipocytokine linked to insulin resistant states in mouse animal models and in humans and predicting the development of type 2 diabetes, has been associated to endothelial dysfunction in new-onset type 2 diabetes." (PMID 22938533, 2012). "Thus, improved AT function may underlie the increased insulin sensitivity and reduced incidence of type 2 diabetes after long-term ARB treatment in subjects at high-risk of developing this disease." (PMID 22768174, 2012). "Hence, increased insulin levels seen in association with type 2 diabetes might lead to aggressive tumor behavior." (PMID 21364956, 2011). "Since HNF-1α protein plays a key role in β-cell function, the reduction in normal HNF-1α activity may compromise β-cell function and further explain the interaction between the HNF1A G319S polymorphism and fasting insulin on the outcome of incident type 2 diabetes observed in our study." (PMID 21208426, 2011). "Physical inactivity is considered as one of the potential risk factors for the development of type 2 diabetes and other metabolic diseases, while endurance exercise training could enhance fat oxidation that is associated with insulin sensitivity improvement in obesity." (PMID 21887385, 2011). "Besides these putative mechanisms, there are multiple defects in insulin secretion and signaling in type 2 diabetes, which might be associated with the low amylase secretion from the pancreas." (PMID 21496338, 2011).
type 2 diabetes (continued). "Mechanistically, it has been hypothesized that the diabetogenic effect of GlcN observed in animal infusion studies is mediated by GlcN augmenting hexosamine biosynthesis in insulin-sensitive tissues, a metabolic pathway that has been implicated in the development of type 2 diabetes 4,5." (PMID 21218504, 2011). "Alcohol consumption may decrease the risk of type-2 diabetes by promoting insulin sensitivity." (PMID 20307313, 2010). "Many of the available oral antidiabetes agents, as well as insulin, are associated with weight gain that contribute to an increase in CV risk and insulin resistance thereby creating a significant challenge in the management of overweight/obese patients with type 2 diabetes." (PMID 20804556, 2010). "Furthermore, nondiabetic individuals carrying the risk G-allele showed increased expression of MTNR1B in pancreatic islets and the MTNR1B risk G-allele has been suggested to increase risk of impaired fasting glycemia and type 2 diabetes through impaired insulin secretion." (PMID 20398260, 2010). "However, this weight loss did notrestore normal insulin pulsatiliy in Type 2 diabetes patients." (PMID 18604303, 2008). "Therefore, an individual with type 2 diabetes may have acombination of deficient secretion and action of insulin." (PMID 19132099, 2008). "Additionally, further study of the mechanisms underlying the increased energy expenditure and increased insulin sensitivity in these mouse models may identify other novel therapeutic targets for human obesity and type 2 diabetes." (PMID 16448557, 2006). "An example of overexpression of an miRNA in type 2 diabetes is miR-200c, which decreases the expression of ETS variant transcription factor 5 (ETV5), causing disruption to insulin exocytosis." (PMID 41174263, 2026). "Specificity declined with age, from 100% in patients < 30 years to 60% in those ≥ 80 years, mainly due to misclassification with insulin-treated type 2 diabetes." (PMID 41899210, 2026). "A growing body of literature suggests that heat therapy improves whole‐body insulin sensitivity in Type 2 diabetics." (PMID 41559866, 2026). "Acupuncture has been proposed as an insulin sensitizer with potential benefits for managing obesity and type 2 diabetes." (PMID 41514462, 2026). "The Treatment Options for Type 2 Diabetes in Adolescents and Youth (TODAY) and the Restoring Insulin Secretion (RISE) studies demonstrated that loss of beta cell function cannot be prevented by metformin monotherapy, 23]." (PMID 41204644, 2026). "Type 2 diabetes mellitus (T2DM) is a chronic metabolic disease characterized by hyperglycemia due to insulin resistance or insufficient insulin production." (PMID 41515283, 2026). "Type 1 diabetes was defined as International Classification of Diseases, 10th Revision (ICD-10) E10 with insulin prescription; type 2 diabetes as ICD-10 E11-E14 with antidiabetic medication use." (PMID 41787464, 2026). "AwiqliTM (insulin icodec-abae), a novel once-weekly basal insulin analog, has recently been approved to improve glycemic control in adults with type 2 diabetes." (PMID 42254168, 2026). "Type 2 diabetes (T2D) is identified as a serious and chronic condition marked by impaired blood glucose levels resulting from insufficient insulin production or an inability of the body to utilize insulin properly." (PMID 41496893, 2026). "Ongoing clinical trials in patients with IGT or Type 2 diabetes have shown an improvement in insulin sensitivity and glucose control, and consolidate the therapeutic potential of ginseng pharmacotherapy." (PMID 41599783, 2026). "These phenotypes mirror those of missense mutations in the insulin B- and A-chains, ranging from those that result in severe MIDY to those that produce only a rather mild adult-onset diabetes phenotype and others that are entirely tolerated genetic variants." (PMID 41516356, 2026).
type 2 diabetes (continued). "Central insulin action in the brain is thought to contribute to metabolic regulation, but the specific hypothalamic nuclei affected in type 2 diabetes (T2D) remain poorly characterized." (PMID 42258747, 2026). "GLP-1 became the focus of incretin therapy because of its strong potentiation of glucose-induced insulin secretion and glucose-lowering efficacy in type 2 diabetes." (PMID 41174263, 2026). "Insulin edema has been described in both type 1 and type 2 diabetes; however, occurrence in slowly progressive type 1 diabetes mellitus (SPIDDM) is exceptionally rare." (PMID 41476905, 2026). "Exogenous insulin therapy has long been the principal treatment strategy for patients with type 1 diabetes and for those in advanced stages of type 2 diabetes." (PMID 41597265, 2026). "In animal models of carotid body hyperactivity CSNX has been shown to reduce excessive sympathetic outflow, lower blood pressure, and in hypercaloric type 2 diabetic rats restore insulin sensitivity." (PMID 41243325, 2026). "Among people with type 2 diabetes each of metformin and insulin is prescribed sooner in people with compared to those without SMI." (PMID 41235789, 2026). "Among adults with type 2 diabetes in Scotland, each of metformin and insulin prescribing is initiated earlier among those with versus without SMI." (PMID 41235789, 2026). "When undergoing ER stress, beta-cell insulin processing becomes less efficient, leading to increased pro-insulin content and secretion, indicative of type 2 diabetes development." (PMID 41386533, 2026). "Inhibition of miR-200c using an antagomir with complementary nucleotides increased glucose-induced insulin secretion (almost threefold) in islets from type 2 diabetes donors." (PMID 41174263, 2026). "Metformin is a first-line oral antidiabetic drug widely used to improve insulin sensitivity and regulate glucose metabolism, particularly in individuals with type 2 diabetes." (PMID 41578026, 2026). "Studies have reported expression of GCG in single-cell sequencing from SC-beta cells and human beta cells and co-expression of insulin and glucagon has been reported in type 2 diabetes." (PMID 41291239, 2026). "For these reasons, when possible, many primary care providers prefer their patients with well-controlled type 2 diabetes to be transitioned from basal insulin to a GLP-1 RA." (PMID 41955563, 2026). "This narrative review examines the prospects for future non-insulin agents and therapeutic approaches in early development that aim to improve glycaemic control in type 2 diabetes." (PMID 41174263, 2026). "Insulin dependence in elderly patients with long-standing type 2 diabetes (T2D) is common due to progressive β-cell decline, and insulin withdrawal is rarely considered." (PMID 42158779, 2026). "Together with clinical observations showing preserved central insulin responsiveness in individuals with type 2 diabetes, these findings highlight peripheral insulin resistance as a key contributor to brain vulnerability in AD." (PMID 41969120, 2026). "Metformin, a widely prescribed antihyperglycemic agent, plays a crucial role in the management of Type 2 diabetes by reducing hepatic glucose production and increasing insulin sensitivity." (PMID 42253768, 2026). "Adults aged ≥18 years with type 1 diabetes or insulin-treated type 2 diabetes and advanced CKD (stage 3b or higher, including dialysis) were eligible." (PMID 42108331, 2026). "This study aimed to assess carbohydrate knowledge in individuals with type 1 diabetes (T1D) and insulin-treated type 2 diabetes (itT2D) using the GluciQuizz tool." (PMID 42124017, 2026). "Fetal hyperinsulinemia, characterized by elevated insulin levels, is a critical condition that can result in neonatal and long‐term metabolic complications, such as obesity, type 2 diabetes mellitus (T2DM), and cardiovascular diseases." (PMID 40920364, 2026).
type 2 diabetes (continued). "Imeglimin is a tetrahydrotriazine that was recently approved to treat type 2 diabetes in Japan (2021) and India (2022) and which has been shown to improve glucose-induced insulin secretion, especially first phase, in clinical trials." (PMID 41174263, 2026). "Across diverse settings (including type 2 diabetes, workplaces, and digital delivery), combined interventions improved glucose control, insulin resistance, lipids, and inflammation, and some benefits occurred even without additional weight loss." (PMID 42211095, 2026). "Disorders of glucose metabolism, particularly type 2 diabetes and obesity, remain major therapeutic challenges because they involve dysfunction across multiple tissues, including pancreatic β-cells, peripheral insulin-sensitive tissues, and immune cells." (PMID 42136085, 2026). "In a series of 8–10 hot water immersion sessions over 14 days, fasting insulin and insulin sensitivity were improved in individuals with type 2 diabetes, though fasting glucose was unchanged." (PMID 41559866, 2026). "Glucagon-like peptide-1 receptor agonists (GLP-1 RAs) are well-established agents in the management of type 2 diabetes, augmenting glucose-dependent insulin secretion, suppressing glucagon, slowing gastric emptying, and promoting satiety." (PMID 41959758, 2026). "Exposures were eight type 2 diabetes-related pathways (n=1,812,017), eight beta cell function indices (n=26,356) and two insulin sensitivity indices (n=53,657)." (PMID 41634175, 2026). "We evaluated associations between neonatal hypoglycemia and breastfeeding.This is a secondary analysis of a randomized controlled trial of metformin versus placebo plus insulin in participants with type 2 diabetes." (PMID 41806854, 2026). "The glucagon peptide 1 receptor (GLP-1R), a class-B-type G protein-coupled receptor (GPCR), is a key therapeutic target for many metabolic disorders, including obesity and type 2 diabetes, due to its central role in glucose homeostasis and insulin secretion." (PMID 42157826, 2026). "Non-insulin treated individuals with type 2 diabetes were identified and categorised by major UK self-reported ethnicity groups: White, Black, South Asian and Mixed/Other." (PMID 41399804, 2026). "Type 2 diabetes mellitus (T2DM) results from a combination of insulin resistance and eventual β cell failure, and the genetic variants involved regulate insulin, adipocyte function, and energy balance." (PMID 41511357, 2026). "Patients with type 2 diabetes (metformin-, insulin-, and diet-controlled; n = 32) were randomized to a 12-week walking intervention (40 min, three times/week; n = 16) or standard care (control group, n = 16)." (PMID 41892724, 2026). "Another reason to consider GLP1 as a monotherapy agent is its insulin sensitizing effect, which targets the insulin resistance of youth-onset type 2 diabetes." (PMID 41204644, 2026). "The impact of heat therapy on skeletal muscle glucose uptake, insulin sensitivity, and metabolism remains a relatively untapped area of research that will be important as we consider the rising epidemic of Type 2 diabetes and other metabolic diseases." (PMID 41559866, 2026). "This review showed that camel milk (200-500 mL/day or 10 g powder BID, 2-14 weeks) improves glycemic control in Type 2 diabetes by lowering fasting and postprandial glucose, HbA1c, and plasma insulin." (PMID 42016254, 2026). "To address these shortcomings and to add novel findings from a contemporary UK setting, we investigated the initiation of prescribing of each of metformin and insulin to adults diagnosed with type 2 diabetes between 2004 and 2022 in Scotland, by SMI status." (PMID 41235789, 2026). "The perturbation flows particularly affect β- and α-cells, which are specialized cells that secrete insulin and glucagon, respectively; their dysfunction is central to type 2 diabetes." (PMID 41465115, 2025).
type 2 diabetes (continued). "Beyond its well-established role in type 2 diabetes, where it regulates GLP−1 metabolism and insulin secretion, DPP4 has also been implicated in the development of fibrosis across multiple organs, including the liver, kidney, and skin." (PMID 41334589, 2025). "Chromium has been purported to improve insulin sensitivity and help manage blood glucose levels, particularly in individuals with glucose intolerance and/or type 2 diabetes." (PMID 40573153, 2025). "In type 2 diabetes, chronic ER stress in insulin-producing pancreatic β-cells impairs their function and ultimately leads to apoptosis via the CHOP pathway, contributing to the decline in insulin production." (PMID 41009381, 2025). "The success of AM supplementation in treating multiple diseases in mouse models has led to two clinical trials in overweight/obese insulin-resistant individuals and patients with overweight/obese type 2 diabetes." (PMID 41277960, 2025). "Fasting glucose regulation seems to be crucial, as these compounds can improve insulin action and secretion, which is key for better glucose balance and preventing metabolic issues like obesity and type 2 diabetes." (PMID 40869270, 2025). "In type 2 diabetes, whey stimulates insulin and incretin hormones (GLP-1, GIP), slows gastric emptying, and reduces postprandial glucose excursions." (PMID 41305580, 2025). "Adiponectin enhances fatty acid oxidation and insulin sensitivity to forestall the onset of type 2 diabetes and cardiovascular diseases." (PMID 40564914, 2025). "Clinical evidence demonstrates that early insulin therapy (2–5 weeks) in individuals newly diagnosed with type 2 diabetes can yield years of glycaemic control, supporting the reversibility of early beta cell dysfunction." (PMID 40768044, 2025). "People with type 2 diabetes usually come to insulin therapy in time, now with a prevalence for insulin administration of ≈50%, thanks to improved management of associated health risks giving longer life expectancy." (PMID 40035222, 2025). "Insulin is used in the treatment of type 1 diabetes and less commonly in type-2 diabetes by binding to insulin receptors on cells to reduce blood glucose levels." (PMID 40564412, 2025). "This post hoc analysis of ONWARDS 1–5 compared the proportion and incidence of physical activity-attributed hypoglycaemia for once-weekly icodec vs once-daily insulin comparators in adults with type 2 diabetes." (PMID 40186685, 2025). "A similar level of insulin-immunoreactive cells, also containing either glucagon or somatostatin, has been reported within human islets and was increased in donors with type 2 diabetes." (PMID 39791735, 2025). "Further studies are necessary to understand why insulin secretion declines with age in order to develop new strategies for the prevention and treatment of type 2 diabetes." (PMID 40002793, 2025). "Exercise training had no impact on fasting BCAAs and did not affect insulin’s ability to reduce plasma BCAAs in any group (studies III and IV) or rescue the attenuated insulin suppression of plasma BCAAs in participants with type 2 diabetes." (PMID 40404819, 2025). "Diabetics cannot regulate their blood glucose levels because of insufficient insulin production (type 1 diabetes) or insulin insensitivity (type 2 diabetes)." (PMID 40572277, 2025). "Type 2 diabetes mellitus (T2DM) is a metabolic disorder characterized by insulin resistance and a deficiency in insulin secretion, leading to elevated glucose concentrations in the bloodstream." (PMID 40895858, 2025). "In another study, insulin antibodies occurred at a relatively low proportion (i.e., 2.22%, 11/495) in adults who were clinically diagnosed with type 2 diabetes based on fasting, random, or 2‐h plasma glucose concentrations during a 2‐h OGTT." (PMID 40470991, 2025). "Type-2 diabetes (T2D) is a chronic disease resulting from inadequate insulin production or impaired insulin function." (PMID 40556930, 2025).